MYC (MYC proto-oncogene, bHLH transcription factor)
Diseases named in the same sentence as MYC in open-access papers (continued):
Sharing a sentence is not in itself a finding about the gene and the disease.
tumor (continued). "Notably, recent studies have shown that MYC influences the host tumor microenvironment and immune effectors in liver, lung and pancreatic cancer, suggesting a role for MYC in immune suppression beyond its activity as a mitogen." (PMID 36323660, 2022). "CRISPR/Cas9-mediated perturbation of a MYC promoter-proximal CTCF binding site in tumor cells leads to reduced chromatin interactions between the MYC promoter and distal SEs present downstream of MYC, indicating that the CTCF docking site is necessary in mediating enhancer–promoter looping." (PMID 35740532, 2022). "In line with the famous “two-hit” hypothesis for tumor development, overexpression of MYC in B-cells would generally induce apoptosis or senescence, making the acquisition of secondary mutations necessary for oncogenic transformation." (PMID 36611833, 2022). "Indeed, de‐activating the oncogene in various MYC‐driven mouse tumor models prompted systemic tumor regression with – among other effects – marked reactivation of anti‐tumoral immune responses." (PMID 36214609, 2022). "Moreover, we detected five different gene amplifications in two different tumor specimens, including MYC (n = 2), PDGFRA, KIT, KRAS, and RICTOR." (PMID 35454843, 2022). "Notably, all 48 critical genes for murine MYC-induced lymphomagenesis are expressed in human lymphoid tissue and most are deregulated in the corresponding tumor." (PMID 36611833, 2022). "MYC amplifications were found in five high-grade tumours establishing its status as a driver of CS." (PMID 36042521, 2022). "SNORA38 was closely association with MYC targets, suggesting that SNORA38 may be involved in tumor cell cycle and related to apoptosis and cell transformation." (PMID 36158687, 2022). "Moreover, we demonstrated ectopic expression of IFITM3 suppressed FOXO3 expression, consequently led to c-MYC induction to promote tumor growth, cell metastasis, cancer stemness as well as chemoresistance." (PMID 35941699, 2022). "First, we utilized a MYC/BCL-XL–driven AML mouse tumor model." (PMID 36874405, 2022). "While the argument can be made that MYC S146L serves as a tissue-agnostic tumor promoter due to the diversity of cancer types it is observed in, we nevertheless sought to interrogate the effect of this substitution in a model more representative of human disease." (PMID 36018850, 2022). "Comparison of the c-MYC gene structure of cancer tissue cells and non-cancerous breast cells from the same patient revealed, in the tumor cells, a specific rearrangement of one of the MYC loci and amplification of the second MYC locus located on the homologous chromosome." (PMID 35269693, 2022). "MYC may also be an important predictor of outcome for immune checkpoint inhibitor therapy in other tumor types (such as urothelial bladder cancer and ccRCC)." (PMID 35760778, 2022). "MYC inactivation increased PD-L1 expression on tumor infiltrating CD11b+Ly6G− myeloid cells but did not significantly alter PD-L1 expression on CD11b+Ly6G+ neutrophils, on CD11c+ dendritic cells, or on tumor cells." (PMID 35760778, 2022). "Importantly, expression of miR-3189-3p in normal breast epithelial cells HME1 did not result in downregulation of c-MYC, suggesting that the activity of the miRNA on c-MYC is specific to tumor cells." (PMID 35642054, 2022). "Additionally, MYC is almost ubiquitously expressed at each stage of tumor development; it can be upregulated through direct transcriptional targeting by many other genes, thereby driving proliferation and therapeutic resistance." (PMID 36704352, 2022). "Additionally, MTORC1 signaling, TNF-alpha signaling and MYC-targets were overexpressed compared to the tumor tissue in vivo." (PMID 35646693, 2022).
tumor (continued). "MYC can coordinate glutaminolysis based on the tumor context and can also regulate Gln anabolism." (PMID 33923299, 2021). "MYC oncogene amplification was also observed in 30% of the AA ESCC tumor samples." (PMID 34285259, 2021). "Here, we identified that gene sets associated with negative regulation upon oncogenic KRAS signaling as well inflammatory responses were downregulated in KPGEMM and KPCRISPR tumor, while tumor cells upregulated MYC target gene signatures and DNA repair pathways." (PMID 33738287, 2021). "Increasing evidence shows that MYC is an essential component for BET-regulated tumor immunity." (PMID 33462181, 2021). "We also checked whether expression levels of MHC I and MYC differ by tumor source and anatomical site based on the “NCI/Hamon Center” patient-derived SCLC lines data set." (PMID 33750914, 2021). "Greater than 20 copies of MYC were detected relative to a 2-copy state for the centromere of chromosome 8 with the amplification signal pattern most consistent with double minute formation (primary tumor: nuc ish(MYC amp)[74/100]; recurrent tumor: nuc ish(MYC amp)[92/100])." (PMID 34895332, 2021). "These molecular subgroups of MB are characterized by a particularly aggressive tumor growth, with a five-year OS of 41% and 50%, respectively, frequent drop metastases to the leptomeningeal spaces, and high-level expression and amplification of MYC." (PMID 34731160, 2021). "Derived from MYC-driven primary MB tumors, it is presently regarded as a cell system at the crossroad between G3 and G4 MB, reflecting in vitro the partial overlap observed between these tumor subgroups in vivo." (PMID 34359754, 2021). "Further analysis of 8q24.2 showed that the amplification of two oncogenes, MYC and NDRG1, located on this fragment might be associated with HRD across tumor types." (PMID 34976815, 2021). "Thus, distinct from tumor cells, MYC instead of NOTCH is a possible upstream transcriptional regulator of SLC transporters in muscle." (PMID 33882453, 2021). "Although Vκ*MYC mice with active-MM demonstrated significant molecular divergence, we identified a subpopulation of cells in every tumour with a shared transcriptional program related to protein translation and the response to amino acid deprivation via the stress-sensing kinase GCN2." (PMID 34732728, 2021). "Fueled by reports that experimental inactivation of MYC promotes tumor regression in mice, there is considerable interest in the idea that MYC inhibitors could form the basis of broadly effective anticancer therapies." (PMID 33416496, 2021). "To ask whether the endogenously expressed MYC is critical for growth, we deleted MYC in sgMGA-KP and control KP tumor lines and found suppression of proliferation in both cases." (PMID 34236315, 2021). "Several preclinical studies have highlighted potent oncogene addiction in MYC-driven tumors, and loss of function analysis in several tumor models (not MYC driven) has suggested a general strong dependency of tumor cells on MYC activity." (PMID 34201047, 2021). "Therefore, as a component of polarity protein, SCRIB has been suggested as a tumor suppressor, and loss of SCRIB induced tumorigenesis in MYC-induced transformed epithelial cells." (PMID 33803371, 2021). "The transcription factor MYC is induced during cell proliferation and tumor formation." (PMID 34440750, 2021).
tumor (continued). "Notably, high levels of CD44, CD133, Nestin and MYC protein were detectable in adherently grown CSC populations from all tumor types as well as in spheres derived from ECSC_b and GSC_c." (PMID 33800955, 2021). "Thus, in addition to CNV-level events, transcriptional heterogeneity in the malignant compartment of Vκ*MYC mice is also driven by other mechanisms, which likely include external contributions from the tumour microenvironment." (PMID 34732728, 2021). "RT-qPCR analysis of GLS and MYC expression showed that both these genes are significantly upregulated in the metastatic tumor cells compared to the cells that originated from the primary tumor site." (PMID 34335968, 2021). "Additionally, knockdown of P5C synthase alone or the PYCRs in concert reversed the effect of c-MYC on the growth of tumor cells." (PMID 34825974, 2021). "Collectively, these data indicate that SQLE is critical for MYC-mediated tumor cell proliferation." (PMID 33791309, 2021). "For the MYC amplifications of Group 3 MB patients, the tumor purity of Group 3 MB with MYC amplifications was significantly different from that of Group 3 MB without MYC amplifications (MYC amplifications vs. MYC balance, p = 0.0086; MYC amplifications vs. MYC deletion, p = 9.8e-05)." (PMID 34925437, 2021). "If that venue is to be pursued, however, we need to place this interaction in biological context, identify the gene networks that are under its control, and determine whether the MYC–HCF-1 interaction is required for tumor initiation, maintenance, or both." (PMID 33416496, 2021). "MYC expression is tightly regulated in normal cells, and tumor cells are often addicted to MYC expression for their growth due to great demand for continued generation of metabolites, thus being more sensitive to MYC inhibition." (PMID 34857874, 2021). "To test this, we inactivated MYC in separate sets of mice at various times post-implantation of cancer cells and used subsets of the 3-compartment model to describe each mouse’s RLuc measurements of total tumor burden." (PMID 33446671, 2021). "It was speculated that the MYC gene should play a role in tumor progression, and inhibiting the expression of MYC gene and changing its regulatory pathway may provide ideas for inhibiting tumor proliferation and metastasis." (PMID 33540574, 2021). "For example, miR-17-92 cluster gene, reported to be activated by MYC, encodes for six distinct miRNAs (miR-17, miR-18a, miR-19a, miR-19b, miR-20a, miR-92) that suppress chromatin regulatory genes and the apoptosis regulator BIM, acting together with MYC to accelerate tumor development." (PMID 34359809, 2021). "Additionally, MYC is involved in glucose/glutamine sensing and mTOR-dependent Akt functions, which regulate the bioenergetic balance of tumor cell growth and survival." (PMID 35029792, 2021). "However, retrospective analysis of clinical data suggested that a standard histological criteria is a more accurate indicator of tumor behavior than assessment of the pattern of c-MYC expression based on immunostaining alone." (PMID 33718147, 2021). "Furthermore, the translation of c-MYC is undoubtedly important in a range of other tumor settings, making this targeting strategy potentially applicable to other MYC-dependent malignancies." (PMID 33855169, 2021). "Amplification of the locus containing the MYC gene has been observed in many tumor types." (PMID 34440124, 2021). "Thus, the association between the TI-signature and MYC/MYCL/MYCN amplification status were examined and the results indicated that the TI-signature score represented the MYC pathway in the tumor cells." (PMID 34122516, 2021).
tumor (continued). "Inhibition of these CDKs may be particularly important for tumours relying on altered transcriptional regulation, such as those driven by oncogenic transcription factors like breast (MYC) and prostate (AR) cancers and Ewing sarcomas (EWS‐FLI1)." (PMID 34092037, 2021). "In addition to the immune compartment, MYC instructs the proliferation of fibroblasts and stellate cells, leading to the characteristic tumor desmoplasia." (PMID 34637026, 2021). "Second, our demonstration that disrupting the MYC–HCF-1 interaction in the context of an existing tumor promotes its regression provides compelling proof-of-concept for the idea that inhibitors of this interaction could have utility as anticancer agents." (PMID 33416496, 2021). "Inhibiting MYC at physiological levels, both directly and indirectly, is able to restore mechanisms regulating key checkpoints in cell cycle progression, leading to tumor regression, senescence, and apoptosis." (PMID 33801599, 2021). "Deregulated MYC overexpression and activation contributes to tumor growth and progression." (PMID 34178666, 2021). "Covalent cross-linking of TRRAP to MYC could permanently sequester TRRAP with the consequence that the equilibrium of TRRAP binding to its tumor suppressor partners is disturbed." (PMID 33937075, 2021). "It is also possible to suppress tumor growth through pharmacologically uncoupling bioenergetic pathways that involve glutamine or glucose metabolism from cellular biomass accumulation induced by MYC." (PMID 33771191, 2021). "Moreover, it has been reported that CDK5 reduces the tumor inhibitory impact of BIN1 by regulating c-MYC Ser-62 phosphorylation in NSCLC." (PMID 34406978, 2021). "Therefore, using the Tet-regulated system and dual-luciferase labeled cells, we were able to monitor total tumor burden (RLuc) and MYC expression (FLuc) at any given time by in vivo imaging." (PMID 33446671, 2021). "This downregulation is particularly pronounced in MYC-amplified tumours." (PMID 34681760, 2021). "Across all TF and cross-tumor entities, MYC exhibits the most frequent drug interactions." (PMID 34637026, 2021). "Most of these studies have so far focused on the targeting of the ATR/CHK1 pathway, with the idea that latent RS in MYC-dependent tumor cells might constantly engage ATR/CHK1 to prevent rampant genomic instability." (PMID 34201047, 2021). "Interestingly, the metabolic reprogramming we observed correlates with high levels of both MYC and E-cadherin in the metastatic cell lines compared to the primary tumour cell line." (PMID 33498690, 2021). "Consequently, treatment of LSCC tumour cells with FT206 resulted in reduced c-MYC, c-JUN, Δp63, and USP28 protein levels, which were restored upon addition of MG132." (PMID 34636321, 2021). "MYC was shown to directly bind to the promoter of PD-L1 and enhanced the expression of PD-L1, regulating the anti-tumor response in mouse tumors and human tumor cells." (PMID 35069587, 2021). "Several lncRNAs are currently known to regulate MYC gene expression in various tumor types." (PMID 34440124, 2021). "It would be interesting to know their effect on tumor MYC levels." (PMID 35582389, 2021). "Our results furtherly indicated that LINC01001 overexpression accelerates crizotinib-resistant NSCLC cell proliferation, inhibits apoptosis, and accelerates tumor growth via IGF2BP2/MYC axis, indicating LINC01001 regulates crizotinib-resistance NSCLC progression by modulating IGF2BP2/MYC axis." (PMID 34630126, 2021). "Moreover, reduction in the percentage of proliferating Ki67-positive tumor cells, decreased MYC expression, and induced apoptosis also occurred in the tumors treated with loaded modified EVs." (PMID 34199901, 2021). "Interestingly, all of these patients likely had MYC-deregulated tumours, with high expression driven by NUTM1 rearrangement, stabilised by FBXW7 mutation or due to elevated MYC copy number or epigenetic mechanisms." (PMID 33311588, 2021).
tumor (continued). "(C) Representative LADC and LSCC tumours stained with c-MYC, c-JUN, and Δp63 antibodies." (PMID 34636321, 2021). "However, some reports show that MNT functions in cooperation with MYC by maintaining cell proliferation, promoting tumor cell survival, and supporting MYC-driven tumorigenesis in cellular and animal models." (PMID 34572909, 2021). "By restraining the JAK/STAT3/c-MYC pathway, metformin could inhibit the transition of normal endothelial cells toward tumor endothelial cells induced by tumor conditioned medium." (PMID 33903283, 2021). "Expression of CD47 in the tumor microenvironment is regulated by oncogenes, including MYC." (PMID 33925464, 2021). "The MYC–host cell factor (HCF)–1 interaction is required for tumor engraftment and maintenance." (PMID 33416496, 2021). "Moreover, knockout of eIF6 in mice avoided MYC-induced lymphomagenesis and prolonged tumor-free survival tumor growth." (PMID 34016142, 2021). "MNT was first described as a MYC antagonist and tumor suppressor." (PMID 34572909, 2021). "Upon MYC inactivation, the majority of tumor cells are eliminated." (PMID 33446671, 2021). "Furthermore, elevated levels of FGFR1 and FGFR3 associated with tumor progression and drug resistance, also correlated with expression of c-MYC, another protein responsible for tumor angiogenesis." (PMID 34830951, 2021). "This was particularly important since release of eIF4A inhibition in patients could result in a burst of MYC expression with potential tumor-promoting consequence." (PMID 34398253, 2021). "MYC inactivation led to tumor reversion in different tumors." (PMID 33958005, 2021). "Hence, alternatives to an MYC blockade have been widely explored to achieve desirable anti-tumor effects, including MYC/MAX complex disruption, MYC transcription, translation inhibition, and MYC destabilization." (PMID 33494392, 2021). "Similarly, CAF secretion of FGF2 in breast cancer can bypass classical hormone receptor signaling inhibited by endocrine therapy to activate ERK1/2 signaling, promote MYC target gene expression and tumor growth." (PMID 34068954, 2021). "(G) LSCC tumours stained with c-MYC, c-JUN, and Δp63 antibodies." (PMID 34636321, 2021). "This may cast some doubt on the necessity for BETi to lower MYC transcription in order to provoke an anti-tumour response." (PMID 33723398, 2021). "Therefore, MYC knockdown enhanced growth arrest and apoptosis in tumor cells both in vivo and in vitro." (PMID 34944772, 2021). "Our recent work suggested that tumor growth inhibition by Pfn1 is mediated at least in part by its nuclear function in repressing SEC-dependent transcription of pro-cancer genes including c-MYC." (PMID 34235154, 2021). "During tumour evolution, high levels of MYC expression can result in increased expression of PD-L1 by direct binding to its promoter, as well as by hijacking the phospho-eIF2a dependent adaptive stress pathway to bypass the post-transcriptional control orchestrated at the 5′-UTR of the PD-L1 mRNA." (PMID 34572910, 2021). "MYC could either directly or cooperate with other oncogenes to regulate the expression of PD-L1 to inhibit the function of immune cells or remodel the tumor microenvironment by recruiting macrophages that promote angiogenesis and reduce T cell infiltration." (PMID 34122516, 2021). "Furthermore, MYC recruits P-TEFb to promoters to enhance transcription of its target genes, and MYC-overexpressing tumor cells are dependent on this activity." (PMID 34207158, 2021). "Interestingly, the analytical results showed high expressions of the MYC/CXCL8/TIMP1 oncogenes in tumor samples compare d to normal samples." (PMID 34440739, 2021).